PPARA (peroxisome proliferator activated receptor alpha)
Diseases named in the same sentence as PPARA in open-access papers (continued):
Sharing a sentence is not in itself a finding about the gene and the disease.
tumor (continued). "Pioglitazone, both the PPARα and PPARγ agonistic component, inhibit carcinogenesis, tumor progression, proliferative capacity of metastasis-initiating stem cells, migration, invasion and remodel the extracellular matrix and angiogenesis." (PMID 38273846, 2023). "As a result, the expression of SCD, a PPARα/γ target gene involved in tumor progression and chemoresistance, was significantly downregulated." (PMID 36472914, 2023). "Peroxisome proliferator-activated receptor-α (PPARα) agonists have a role in anti-tumor therapy and MG53 attenuates inflammatory responses in cardiomyocytes by upregulating PPARα expression." (PMID 38033997, 2023). "PPARα inhibitor can inhibit the proliferation of tumor cells by regulating CPT1 (essential for fatty acid metabolism and energy production)." (PMID 37064872, 2023). "PPARα signalling was reported to preserve cytotoxic function of tumour infiltrating CD8+ T cells through FAs catabolism under hypoglycaemic and hypoxic TME." (PMID 37700501, 2023). "Collectively, these results suggest that the anti-tumor function of PPARα involved not only SREBP1, but also p21/p27, antioxidant enzymes, and ARID1A." (PMID 37305395, 2023). "PPARα/γ agonists provided tumor-type agnostic biomodulatory efficacy across different histologic neoplasias." (PMID 38273846, 2023). "Collectively, these findings suggest that the tumor suppressor function of PPARα is mediated by a reduction in the expression of SREBP1." (PMID 37305395, 2023). "Mechanistically, PPARα/δ agonists inhibited mTOR-mediated glycolysis, thereby precluding the formation of the “synapse” between NK and tumor cells." (PMID 37686465, 2023). "The present study demonstrated that the immunohistochemical expression of nuclear PPARα was lower in EMC than in normal endometrial tissues, suggesting the tumor suppressive nature of PPARα." (PMID 37305395, 2023). "Tumor-derived exosomes carrying fatty acids significantly activate PPARα in TIDCs, resulting in increased intracellular lipid content and mitochondrial respiration, driving immune dysfunction and cytotoxic T-cell activation." (PMID 37251321, 2023). "It will be interesting to determine the extent that genetic or pharmacological inhibition of PPARA-dependent SLC47A1 expression enhances ferroptosis-mediated tumor suppression in vivo." (PMID 36575162, 2022). "An outstanding report evidenced that PPARα-expressing granulocytes, mainly neutrophils, are required for tumor growth." (PMID 35954274, 2022). "Compared to non-tumor tissues, human colorectal tumor tissues display lower levels of PPARα mRNA and protein and higher levels of DNMT1 and PRMT6." (PMID 35743814, 2022). "Peroxisome proliferator-activated receptor-α (PPARA), one of the core factors in the lipid metabolism, has been proven to participate in the development of tumor." (PMID 35264957, 2022). "In line with our in vitro studies, PPARA-knockdown (PPARAKD) or SLC47A1-knockdown (SLC47A1KD) MIA PaCa2 cells were more sensitive to IKE-induced tumor suppression compared to control groups in vivo." (PMID 36575162, 2022). "Several nuclear hormone receptors showed changed expression in tumours with high levels of ERBB2 with some being elevated (ESRRA) whereas others were either unchanged (HNF4A) or showed reduced levels (PPARA)." (PMID 36153371, 2022). "Fatty-acid-carrying tumor-derived exosomes (TDEs) activate PPARα, which, in turn, leads to excess lipid-droplet biogenesis and enhanced FAO, provoking a metabolic shift to mitochondrial oxidative phosphorylation and dendritic-cell immune dysfunction." (PMID 35954274, 2022). "Menin, the product of the MEN1 (multiple endocrine neoplasia type 1) tumor-suppressor gene was shown to physically interact with the PPARα protein to control the expression of genes involved in fatty-acid oxidation." (PMID 35954274, 2022). "A recent study supported that the Glut-1 inhibition by PPARα contributes to tumor growth and chemo-resistance." (PMID 36507526, 2022).
tumor (continued). "PPARα is clearly involved in both chronic inflammation, facilitating tumor progression and treatment resistance, and acute inflammatory reactions, often leading to anti-tumor immune responses." (PMID 35954274, 2022). "PPARα activation supports the binding of HIF-1α to the von Hippel–Lindau tumor suppressor, thereby inducing HIF-1α degradation through the ubiquitin–proteasome pathway." (PMID 35954274, 2022). "In this study, H. parainfluenzae and N. flavescens downregulated LXR/RXR, PPARα/RXRα and PPAR signaling, which are known to have tumor suppressive effect." (PMID 35600164, 2022). "Consistent with other studies, PPARα diverted energy away from Warburg-based tumor energy metabolism to lipogenesis to inhibit cell proliferation and tumor progression." (PMID 35534547, 2022). "The administration of this natural product inhibited tumor growth by downregulating PPARα, PPARγ, FABP1, FABP4, and FABP5." (PMID 36296934, 2022). "In terms of PPARα, synthetic PPARα agonists such as fenofibrate and Wy-14643 have demonstrated suppressive effects on endothelial cell proliferation, neovascularization, and tumor xenograft growth." (PMID 33946986, 2021). "In HIF-1α-knocked-out murine models, the anti-tumor immune responses of CD8+ TILs improve through the activation of peroxisome-activated receptor α (PPARα) signaling and also elevated metabolism of fatty acids." (PMID 33532902, 2021). "All these results showed that PPARα pathway plays a positive role in inhibiting tumor, which is consistent with our findings." (PMID 33414412, 2021). "Along with high levels of methylation of PRMT4, PRMT5, PRMT7, and hnRNPA1 in tumor samples, changes in gene alternative splicing were observed, such as those for PPARA, SREBF2, RAB27B, and WDPCP in BRCA, CRC, and PC samples." (PMID 33782401, 2021). "As a key molecule of metabolic regulation, PPARα can be used as a target of immunotherapy and has a great potential in anti-tumor therapy." (PMID 33732237, 2021). "Through the GSEA analysis, we found that the PPARα pathway was activated in tumor samples with higher ACOX2 expression." (PMID 33414412, 2021). "Further, PPARα/γ agonists regulate tumor cell metabolism, proliferation and down-regulate inflammation." (PMID 33796020, 2021). "On the one hand, AMPK inhibits mTORC1, and on the other hand, it collaborates with PPARα to reduce the expression of key enzymes of glycolipid and glutamine metabolism and inhibit glycolytic, thus specifically killing tumor cells." (PMID 33918992, 2021). "For peroxisome proliferator-activated receptor alpha (PPAR α) expression, comparing both tumour-bearing groups, the AW relative expression was diminished in relation to WW (WW < AW)." (PMID 34940589, 2021). "PPARα activation can induce apoptosis and tumour cell death, preventing tumour expansion and inflammation." (PMID 34638914, 2021). "The PFOS exposure combined with an HFD, which increased tumor growth, induced transcriptomic changes in PPARα-target genes and genes involved in chromatin organization that, in turn, regulate transcription." (PMID 34836157, 2021). "In our tissue sample collection, we detected comparable levels of PPARα in tumours in comparison to adjacent normal tissues." (PMID 34572440, 2021). "The peroxisome proliferator-activated receptor (PPAR) nuclear receptors are composed of three family members: PPARα, PPARβ, and PPARγ and evidence has shown their context-specific oncogenic and tumor-suppressive roles." (PMID 33482915, 2021). "It was found that the protein expression level of PPARα of tumor sections was retarded by berberine in the MGC803 xenograft models." (PMID 32328135, 2020). "Addition of the cyclooxygenase (COX) inhibitor Indomethacin neutralized the undesired effects of AVE8134 and restored the beneficial anti-tumor properties of PPARα agonism." (PMID 32785018, 2020).
tumor (continued). "In contrast to these findings in human tumors, an elegant in vivo study by Kaipainen and colleagues demonstrated that PPARα favors tumor progression in mice." (PMID 32785018, 2020). "They further demonstrated a reduced endothelium-associated epoxygenase expression in the PPARα agonist administered animals, concluding that the tumor-angiogenesis inhibition by PPARα activation involves reduced vascular expoxygenase expression." (PMID 32785018, 2020). "In this study, we detected the expression of PPARα in the heart and tumor tissues of tumor-bearing mice treated with DOX." (PMID 33132907, 2020). "Tumor vascularization was inhibited in wildtype, but not in PPARα knockout animals, which confirmed the repression of PPARα through NOX1 as an important event in favor of enhanced tumor angiogenesis." (PMID 32785018, 2020). "In this study, three different types of tumor cells were used to test the effect of PPARα activation on their ability of growth." (PMID 33132907, 2020). "Inhibition of TSP-1 restored tumor growth and bone marrow transplantation and granulocyte depletion experiments showed that PPARα expressing granulocytes, probably myeloid derived suppressor cells, are critically involved in tumor angiogenesis and growth." (PMID 32785018, 2020). "This pathway is known to control the expression of genes involved in lipid metabolism and inflammation, with increasing evidence that PPARα/γ inhibits tumor progression and acts as a tumor suppressor." (PMID 32849808, 2020). "11-HETE in contrast promote angiogenesis and tumor growth, therefore neutralizing the beneficial effect of the PPARα agonist AVE8134." (PMID 32785018, 2020). "The authors contribute this paradox of PPARα effect to a bi-phasic dose-response curve of host tissue: Both, very high, or, in contrast, very low concentrations of PPARα result in suppression of tumor angiogenesis." (PMID 32785018, 2020). "Herein, we showed GPER, alone and together with PPARα, effected estradiol secretion by tumor Leydig cells." (PMID 32180008, 2020). "To further verify the role of PPARα signaling in regulating DC function, we sought to use PPARα−/− DCs as a vaccine to treat the tumor." (PMID 33086073, 2020). "CYP2C9 was found to express in the vasculature of several human tumor samples and be the regulatory target of human peroxisomal proliferator-activated receptor-alpha (PPARα), which have anti-angiogenic and anti-tumorigenic properties." (PMID 33192522, 2020). "Blocking PPARα signaling with specific inhibitors restores the function of DCs and improves anti-tumor immunotherapy." (PMID 33086073, 2020). "Next, we tested the effects of PPARα activation combined with DOX therapy on tumor cells in vitro and in vivo." (PMID 33132907, 2020). "In our mice, lower plasma levels of these fatty acids occurred with tumor progression and lower levels of PPARα in the tumors." (PMID 32913449, 2020). "We found that the PPARα−/− DC vaccine offered an improved anti-tumor effect compared with WT DC vaccine in the MC38-OT I tumor model." (PMID 33086073, 2020). "In keeping with these findings in surgical tumour specimens, PPARα KD in GSC was found to significantly reduce the protein expression of EGFR in vitro." (PMID 30565681, 2019). "PPARα agonists exhibited a reduction in tumour growth and vascularization by suppressing Cyp2c44 expression, which connects them with clinical tumor treatment." (PMID 31791289, 2019). "The novel PPARα agonist AVE8134 showed advantages at security in tumor treatment, although its anti-tumor effect was inferior to wyeth-14,643." (PMID 31791289, 2019). "AVE8134 is a new synthetic PPARα agonist that has excited many researchers given its anti-angiogenesis and anti-tumour properties, as well as its high PPARα affinity and low hepatotoxicity." (PMID 31791289, 2019).
tumor (continued). "Peroxisome proliferator-activated receptor alpha (PPARα) is known to regulate the expression of genes involved in lipid and glucose metabolism, inflammatory/vascular pathways, and tumor activity." (PMID 31724941, 2019). "PPARα agonists including fenofibrate, suppress tumor growth through angiogenesis inhibition and it is demonstrated that the antiangiogenic activity of PPARα ligands is specifically dependent on the activation of this pathway." (PMID 31089369, 2019). "Expression of gankyrin, C/EBPα, and PPARα were analyzed in tumor tissues of patients using real-time PCR." (PMID 29636686, 2018). "Wy-14643, a PPARα agonist, was shown to reduce tumor vascularization and growth through the inhibition of endothelial cell proliferation in mice." (PMID 29445990, 2018). "The relationship between gene transcription regulated by PPARα and tumor metabolism can determine oncogenic or oncosuppressive effects." (PMID 29966227, 2018). "Recent studies have discovered additional roles for PPARα in cell proliferation and metabolism, as well as tumor progression." (PMID 29862267, 2018). "Results from multiple syngeneic and xenograft mouse models suggest PPARα blockade has intrinsic and extrinsic anti-tumor activity and induces tumor-specific immunity." (PMID 30400835, 2018). "The possible roles of C/EBPα, PPARα and gankyrin in the protective effect of arctigenin in the HepG2 cell-xenografted mice were investigated by IHC staining in tumor tissues of each group of mice." (PMID 29636686, 2018). "Western blot analysis by using tumor lysates showed that silenced PPARα reduced LC3-II levels and increased Bcl2 protein levels." (PMID 30519260, 2018). "Peroxisome-proliferator-activated receptors (PPARs) line up in the group of nuclear receptors and encompass three receptors PPARα, PPARγ, and PPARδ, which concertedly and multifaceted have impact on regulating tumor growth." (PMID 30424016, 2018). "TPST-1120 mediated PPARα antagonism resulted in potent anti-tumor immune responses and significant tumor regression, either as a monotherapy or in combination with chemotherapy or anti-PD1." (PMID 30400835, 2018). "Even though the PPARs family contains PPARα, PPARγ and PPARδ, they serve as different functions in tumor development." (PMID 28948004, 2017). "Among the ligands, we identified betulinic acid (BA), a compound already known for its anti-inflammatory, anti-tumour and antidiabetic properties, as a PPARγ and PPARα antagonist." (PMID 28720829, 2017). "The PPARα agonist fenofibrate suppresses tumor growth and angiogenesis by reducing endothelial cell proliferation and VEGF production and increasing endostatin." (PMID 27835866, 2016). "Linear regression analysis showed that PPARα expression was negatively correlated with the advancing of tumor development (P = 0.003)." (PMID 26869356, 2016). "A 0–2, 2–4, 4–6 fold induction in PPARα expression was observed in 8, 10 and 14 tumor sections, respectively." (PMID 26621841, 2016). "HILPDA is a direct target of HIF-1α and PPARα, and elevated expression in hypoxia increases the number of lipid droplets in tumor cells." (PMID 27765905, 2016). "Bioluminescence imaging showed tumor growth stasis in the overexpressing PPARα group compared with the control group and on day 10, a statistically significant difference in tumor volume emerged between the 2 groups." (PMID 27835866, 2016). "PGE2 induces inflammation, and ligand-induced PPARα activation inhibits this inflammation around tumor cells." (PMID 25734181, 2015). "We found that inhibition of PPARA expression, by an siRNA (siPPARA), induced the ability of SNU-449 cells to form colonies in soft agar and increased their cellular invasiveness, suggesting that PPARA has a tumor suppressive function in HCC." (PMID 26206264, 2015). "PPARα suppresses tumor cell growth by inhibiting cell proliferation and inducing cell apoptosis via direct targeting IκBα and NF-κB signaling pathway." (PMID 25327562, 2014).
tumor (continued). "A total of 1,100 genes were differentially expressed (fold-change ≥ 2) in PPARα-/- mice (tumor/normal) compared with WT animals, in which 566 and 544 genes were up-regulated and down-regulated, respectively." (PMID 25327562, 2014). "The anti-inflammatory and anti-angiogenic effects of PPARα also promote the suppression of tumor growth by improving microenvironment." (PMID 25327562, 2014). "PPAR signaling provides a survival advantage to BC cells upon loss of attachment, and activation of PPARA with the chemical agonist compound Wy14643 reduces the development of malignant mammary tumors in a tumor-prevention setting." (PMID 24867881, 2014). "We recently reported that PPARα promotes tumor MS formation and the expression of the MS growth factor Jagged1." (PMID 23372804, 2013). "Given its role in these latter processes, PPARα has been suggested to contribute to tumor formation and/or progression." (PMID 22991505, 2012). "By analogy with autophagy, forced up- or downregulations of PPARα function by genetic manipulation or drug intervention would be detrimental for tumor-host stroma symbiosis through here dysregulation of angiogenesis pathways." (PMID 22654896, 2012). "From these observations, we conclude that NOX1 promotes tumor angiogenesis by inhibiting the anti-angiogenic factor PPARα." (PMID 21326871, 2011). "In different tumor models, activation of PPARα by agonists blocks tumor growth and angiogenesis by reducing production of proangiogenic factors such as VEGF or epoxyeicosatrienoic acids." (PMID 21326871, 2011). "Administration of a novel NOX-specific inhibitor reduced angiogenesis and tumor growth in vivo in a PPARα dependent manner." (PMID 21326871, 2011). "PPARα knockout monocyte/macrophages exist in a highly inflammatory state producing large amounts of thrombospondin-1 and inhibiting tumor growth." (PMID 22028915, 2011). "This opens an opportunity for the use of PPARα agonists, including fenofibrate, since it should be selectively toxic for tumor cells and relatively harmless for cells with normal mitochondrial function." (PMID 20569465, 2010). "Since other members of this family, such as PPARG, exhibit a tumor suppressor-like phenotype, it is possible that PPARA can act as a tumor suppressor in hematological malignancies." (PMID 20052266, 2010). "Gene expression data highlighted the PPARα/RXRα Activation Pathway as down-regulated in the tumor samples." (PMID 20799942, 2010). "In this sense, PPARα-mediated anti-inflammatory actions can be responsible for theirpotential chemopreventive effects in tumor progression." (PMID 18670614, 2008). "Paradoxically, PPARα knockout impaired tumor growth in mice,because it resulted in a strong inflammatory response and production of anti-angiogenic factors, likeTSP-1 and endostatin." (PMID 18551186, 2008). "Farnesolalso stimulates PPARα-dependentdifferentiation in epidermal keratinocytes.Topical PPARα ligandshave weak preventive effects on tumor promotion in mouse skin, despiteupregulation of PPARα inuntreated tumors compared with normal epidermis." (PMID 18483618, 2008). "Although the mechanisms whereby PPARα directly prevents tumor cell functions havenot been investigated in details, potential targets have been identified." (PMID 18725983, 2008). "Wy-14643-mediatedantitumoral and anti-angiogenic responses on tumor and endothelial cells areabsent in PPARα KO mice." (PMID 18670614, 2008). "They demonstrated that PPARα depletion in the host significantlyreduced tumor growth and metastasis." (PMID 18509489, 2008). "Theobservation that PPARα is expressed by tumor cells started studies of the role of thisnuclear receptor and itsligands on the prevention of tumor cell proliferation in vitro and in vivo." (PMID 18725983, 2008). "In particular, AMPK mutations disrupted thepolarity of the epithelium and triggered tumor-like hyperplasia, againsupporting the notion of a possible cooperation between PPARα and AMPK." (PMID 18509489, 2008).